HIF1A (hypoxia inducible factor 1 subunit alpha)
Diseases named in the same sentence as HIF1A in open-access papers (continued):
Sharing a sentence is not in itself a finding about the gene and the disease.
chronic myeloid leukemia (16 papers, 2016 to 2026). "Nuclear accumulation of HIF-1α is impaired by curcumin, in company with an abatement of cellular factors associated with glucose metabolism under non-hypoxic conditions, suggesting the therapeutic potential of curcumin for chronic myelogenous leukemia." (PMID 34575983, 2021). "In summary, this study shows the critical role of selective targeting of components of the HIF1α signaling pathway for the complete eradication of chronic myeloid leukemia cells." (PMID 41520505, 2026). "For instance, HIF‐1α has been reported as a crucial driver of chronic myeloid leukaemia (CML) development induced by the BCR‐ABL oncogene." (PMID 32667731, 2020). "In addition, curcumin increases miR-22 that directly targets IPO7 in chronic myelogenous leukemia cells, indicating that curcumin modulates HIF-1α activity via the miR-22/IPO7 axis." (PMID 34575983, 2021). "Furthermore, our group previously demonstrated that IPO7 is responsible for HIF-1α nuclear translocation in chronic myelogenous leukemia cells." (PMID 30781795, 2019). "To test the hypothesis that the activation of HIF signaling could compromise the anti-cancer effect of BIX-01294 in chronic hypoxia, we used acriflavine (ACF), which is known to inhibit HIF1α and 2α and has shown therapeutic potential for use against chronic myeloid leukemia." (PMID 29145444, 2017). "In chronic myeloid leukemia cells, curcumin inhibits HIF-α activity through the miR-22/IPO7/HIF-1α signaling axis, which synergistically downregulates the enzymatic activities of multiple glycolytic enzymes, pentose phosphate pathway enzymes, and HIF-1α target genes." (PMID 41515171, 2025). "In chronic myelogenous leukemia (CML) and B-cell leukemias, miR-21 is upregulated in response to radiation and influences downstream targets such as PTEN, vascular endothelial growth factor (VEGF), and hypoxia-inducible factor-1α (HIF1-α)." (PMID 41425255, 2025). "In chronic myelogenous leukemia (CML), curcumin was found to up-regulate the expression of miR-22 and down-regulate its target gene importin 7 (IPO7), thus affecting the nuclear transport of HIF-1α." (PMID 33109235, 2020).
Glucose intolerance (16 papers, 2012 to 2024). Glucose intolerance (GI) can be defined as dysglycemia that comprises both prediabetes and diabetes. "Interestingly, deletion of the Hif1a gene in β-cells causes impaired insulin secretion and glucose intolerance in mice with a decreased expression of Slc2a2 (encoding GLUT2) and Gck (encoding glucokinase)." (PMID 38673770, 2024). "Unlike high-, lower DS or switch to restricted chow diet abolished HIF1α levels and reversed glucose intolerance of PFKFB3βKO DS mice." (PMID 35318430, 2022). "Targeted disruption of Hif1α in pancreatic beta-cells resulted in glucose intolerance, impaired GSIS, and beta-cell dysfunction." (PMID 28774305, 2017). "The C57BL/6 mice with β cell–specific HIF-1α disruption exhibited glucose intolerance which developed more severe on a HFD." (PMID 28698587, 2017). "The expression of a constitutively active form of HIF-1α in adipocytes conferred glucose intolerance and the disruption of HIF-1α in adipocytes improved glucose tolerance, indicating that HIF-1α expression in adipocytes deteriorates glucose tolerance." (PMID 24705496, 2014). "Β-cell-specific Hif1a knockout mice exhibit impaired insulin secretion and glucose intolerance." (PMID 38673770, 2024). "However, it was also reported that the inhibition of HIF-1α in adipocytes together with the expression of a dominant negative form of HIF-1α induced glucose intolerance." (PMID 24705496, 2014). "Moreover, high-fat diet-induced glucose intolerance in mice was improved by HIF-1α activation." (PMID 36139067, 2022). "To assess whether the glucose intolerance of Fh1βKO mice is mediated by HIF1α stabilization, we crossed Fh1βKO and Hif1αfl/fl mice to produce β cell-specific deletion of both Fh1 and Hif1α (Fh1Hif1αβKO mice)." (PMID 28954230, 2017). "Although some studies have shown that the expression of HIF-1α in adipocytes induces glucose intolerance, the mechanisms are still not clear." (PMID 24705496, 2014).
emphysema (15 papers, 2011 to 2026). "It is one of three isoforms that target the hypoxia inducible factor 1 alpha (HIF1α) transcriptional complex for degradation in response to hypoxia, with HIF1α degradation implicated in emphysema pathogenesis through VEGF pathways." (PMID 24498427, 2014). "A reduction in the endothelium in patients with emphysema may be caused by reduced levels of Hypoxia Inducible Factor-1α (HIF-1α) and Vascular Endothelial Growth Factor (VEGF)." (PMID 34356894, 2021). "Chronic exposure to airborne carbon black ultrafine also activated the HIF-1α axis, which increased glycolysis in M1 macrophages, leading to emphysema." (PMID 40880642, 2025). "The resulting sequelae, such as emphysema and fibrosis, can result in chronic hypoxia that maintains the expression of HIF-1α, decreasing CCL18 and up-regulating IL-12p40." (PMID 33802081, 2021). "HIF-1α overexpressing CC-LR mice had significant emphysema, and they also showed potentiated tumorigenesis, angiogenesis, and cell proliferation accompanied by an invasive metastatic phenotype." (PMID 30250643, 2018). "Concomitant treatment with S1P normalizes the ceramide-S1P balance in the rat lungs and increases HIF-1α protein expression via activation of sphingosine kinase 1; as a consequence, S1P salvages fenretinide induced emphysema in rat lungs." (PMID 23326540, 2013). "Having reported that HIF-1α and VEGF operate as lung structure maintenance factors, in particular that HIF-1α protein expression was suppressed in the lungs from patients with COPD/emphysema, we next investigated whether the expression of HIF-1α and VEGF was affected by fenretinide treatment." (PMID 23326540, 2013). "In conclusion, Fe2+ chelation-mediated HIF-1α stabilization and VEGF stimulation via local lung delivery of CDSO3 can reverse established emphysema by promoting cell growth and survival." (PMID 41972567, 2026). "Levels of HIF-1α and VEGF appear to be related to COPD disease severity: both are correlated with FEV1 percentage predicted in patients with emphysema." (PMID 34356894, 2021). "Reduced expression of HIF1α has been detected in the emphysema lung tissues in severe COPD patients, suggesting deregulation of HRE activities occurred in HIF1α targeting genes such as LO under this condition." (PMID 21318022, 2011). "VEGF and LOX are also coregulated by the Cu-dependent activation of HIF-1α, the absence of which contributes to emphysema (shown in rat lungs) and involves histone deacetylase HDAC2-mediated expression of HIF-1α, VEGF." (PMID 32708046, 2020). "VEGF levels might be reduced in such patients as Hypoxia Inducible Factor-1α (HIF-1α), a major transcription factor of VEGF, is also reduced in patients with emphysema." (PMID 28100233, 2017). "Levels of HIF-1α and VEGF may be related to disease severity: both are correlated with FEV1 percentage predicted in patients with emphysema." (PMID 28100233, 2017). "At least in rats emphysema associated with decreased expression of HDAC2, HIF-1α and VEGF is not due to inflammation." (PMID 23326540, 2013). "Decreased mRNA levels and expression of HIF-1α protein were observed in lung tissue from patients with severe COPD, which correlated with reduced VEGF and VEGFR2 expression, and may relate to the severity of emphysema." (PMID 36994416, 2023). "We have further shown that deleting HIF-1α in the airway epithelium results in significant tumor reduction and reduced angiogenesis while its overexpression in the epithelium has the opposite effect, resulting in COPD-type inflammation, emphysema and tumor progression." (PMID 30250643, 2018). "Interestingly, similar studies looking at the expression of HIF-1α and VEGF in patients with chronic bronchitis (rather than emphysema) have shown HIF-1α and VEGF are increased in this patient group." (PMID 28100233, 2017).
emphysema (continued). "Therefore, we hypothesized that S1P may induce HIF-1α in the lung tissue and may induce HIF-1α target genes and proteins, and thus may protect the lung against emphysema development." (PMID 23326540, 2013).
endotoxemia (15 papers, 2013 to 2025). "The enhanced expression of Drp1 and suppressed expression of Mfn2 caused by endotoxemia and MV at VT = 10 mL/kg were substantially reversed in HIF-1α-deficient mice." (PMID 35163007, 2022). "The effects of MV on mitochondrial damage, autophagosome formation, and diaphragm function in mice with endotoxemia treated with 10 mL/kg MV were substantially attenuated in HIF-1α-deficient mice (p < 0.05)." (PMID 35163007, 2022). "Notably, dysregulated autophagy and subsequent autophagosome formation associated with mitochondrial dysfunction during MV and endotoxemia are mitigated by HIF-1α gene knockout." (PMID 35163007, 2022). "Moreover, we investigated the role of HIF-1α in mediating the pathogenic mechanisms of VILI with endotoxemia." (PMID 32353952, 2020). "However, whether miR-674-5p modulates HIF-1α in intestinal injury caused by endotoxemia remains to be answered." (PMID 32550011, 2020). "Several studies have shown that a conditional HIF1α or HIF2α knock-out in myeloid cells protects against LPS-induced endotoxemia." (PMID 37006237, 2023). "Although mitochondrial dysfunction is demonstrated to be involved in the pathophysiology of diaphragm injury in critical illness, the interplay between HIF-1α and mitochondria during MV or endotoxemia is not well known." (PMID 35163007, 2022). "In response to endotoxemia, myeloid HIF-1α appears to play a detrimental role, given that myeloid deletion of HIF-1α is protective against LPS-induced mortality and septic shock." (PMID 35053299, 2022). "Mitochondria are a dominant source of diaphragmatic ROS in response to hypoxia and also upstream regulators controlling the HIF-1α signaling pathways facilitating diaphragm muscle injury during MV or endotoxemia." (PMID 33567713, 2021). "Positive results of immunohistochemical staining for HIF-1α were substantially increased in the diaphragm muscle fibers of the mice with endotoxemia treated with VT = 10 mL/kg compared with mice in the other MV treatment groups and the control group." (PMID 33567713, 2021). "A modest reduction of arterial hypoxemia was noted in our animal model of endotoxemia with MV; however, HIF-1α expression was intensely activated in lung and diaphragm tissues under MV." (PMID 33567713, 2021). "The upregulation of HIF-1α mRNA expression was more substantial in mice with endotoxemia subjected to VT = 10 mL/kg than in mice in the other MV treatment groups and the control group." (PMID 33567713, 2021). "Western blot analyses revealed increased HIF-1α expression in mice with endotoxemia treated with high-tidal-volume MV compared with the other MV treatment groups and the nonventilated control mice." (PMID 32353952, 2020). "This was supported by the evidence that the expression of miR-674-5p was abrogated in the absence of HIF-1α in LPS-treated cells, suggesting that control of the HIF-1α/miR-674-5p pathway exerts cyto-protective effects in endotoxemia-induced intestinal injury." (PMID 32550011, 2020). "The upregulation of HIF-1α mRNA expression was larger in mice with endotoxemia treated with high-tidal-volume MV compared with the other MV treatment groups and the nonventilated control mice." (PMID 32353952, 2020). "MiR-674-5p was markedly increased in intestinal epithelial cells (IECs) during endotoxemia and its induction depended on hypoxia-inducible factor-1α (HIF-1α)." (PMID 32550011, 2020). "HIF-1α-dependent glycolytic pathway is essential for the anti-inflammatory effect of ouabain during endotoxemia." (PMID 31182997, 2019). "Moreover, the increase in HIF-1α expression in mice with endotoxemia treated with VT = 10 mL/kg was substantially reduced by inhibition with enoxaparin." (PMID 33567713, 2021). "C57BL/6 mice, either wild-type or HIF-1α–deficient, were exposed to MV with or without endotoxemia for 8 h." (PMID 33567713, 2021).
endotoxemia (continued). "Positive results of immunohistochemical staining for HIF-1α were substantially increased in the airway epithelial cells of the mice with endotoxemia treated with high-tidal-volume MV compared with the other MV treatment groups and the nonventilated control mice." (PMID 32353952, 2020). "Moreover, the increase of HIF-1α expression in mice with endotoxemia treated with high-tidal-volume MV was substantially reduced by inhibition with enoxaparin." (PMID 32353952, 2020). "We then assessed whether LPS affects AGE-induced HIF-1α upregulation, since a hypothetical synergy for HIF-1α expression in the proximal tubule could contribute to better recovery of renal function in diabetic mice after experimental endotoxemia." (PMID 23984430, 2013). "Less is known about the potential role of HIF-1α in AKI due to endotoxemia." (PMID 23984430, 2013). "In the present study, we showed that ouabain can significantly inhibit the upregulation of HIF-1α at the protein level, revealing that the overexpression of HIF-1α can reverse the anti-inflammatory effect of ouabain during endotoxemia." (PMID 31182997, 2019). "CYP2E1-mediated ROS can also stimulate endotoxemia and elevate serum levels of LPS, which can travel to the liver, upregulating pro-inflammatory mediators, including tumor necrosis factor-alpha (TNF-α) and hypoxia-inducible factor 1-alpha (HIF1-α)." (PMID 38247468, 2023). "Western blot analyses revealed upregulated HIF-1α but downregulated PHD2 in mice with endotoxemia subjected to VT = 10 mL/kg in contrast to those without endotoxemia subjected to VT = 10 mL/kg and nonventilated control mice." (PMID 35163007, 2022). "MV with endotoxemia augmented VIDD and mitochondrial damage, which presented as increased oxidative loads, dynamin-related protein 1 level, mitochondrial DNA level, and the expressions of HIF-1α and light chain 3-II." (PMID 35163007, 2022). "Understanding the relationships between HIF-1α and VIDD in a murine model of endotoxemia may be helpful in the development of potential therapeutic strategies targeting these pathways in the vital areas of ALI and ventilator dependence." (PMID 33567713, 2021). "MV with endotoxemia aggravated VIDD, as demonstrated by increased interleukin-6 and macrophage inflammatory protein-2 levels, oxidative loads, and the expression of HIF-1α, calpain, caspase-3, atrogin-1, muscle ring finger-1, and microtubule-associated protein light chain 3-II." (PMID 33567713, 2021). "Elaboration of the HIF-1α/miR-674-5p/XBP-1 signaling pathway not only provides novel and important insight into the pathogenesis of intestinal injury by endotoxemia or endotoxemia, but also suggests a novel miRNA-based therapeutic target for prevention and treatment." (PMID 32550011, 2020).
Ewing sarcoma (15 papers, 2010 to 2025). A small round cell tumor that lacks morphologic, immunohistochemical, and electron microscopic evidence of neuroectodermal differentiation. "EWS-FLI1, the genetic hallmark of Ewing sarcoma, and HIF-1α were found to collaborate in both synergistic and antagonistic ways to regulate cellular metabolism under hypoxia." (PMID 24391834, 2013). "To confirm that HACE1 tumor suppressor activity is linked to its ability to reduce HIF1α levels, we performed soft agar colony assays using the SKNEP1 human Ewing sarcoma cell line that lacks endogenous expression of HACE1." (PMID 33603169, 2021). "In fact, we have searched several original articles, which investigated the relationship between HIF-1α and Ewing sarcoma." (PMID 30782196, 2019). "In Ewing sarcoma cells, siRNA interference of HIF1-α in vitro reduces the hypoxic induction of VEGF." (PMID 29098360, 2018). "For example, specific down-regulation of HIF-1α by RNA interference significantly enhanced apoptosis under hypoxia by preventing the hypoxia-mediated increase in GLUT-1 in Ewing's sarcoma and rhabdomyosarcoma." (PMID 28558056, 2017). "Downstream transcription of transcripts containing the VEGF and GLUT-1 hypoxia-response element (HRE) was HIF1α-dependent in Ewing’s sarcoma, but regulated by both isoforms in osteosarcoma." (PMID 24216979, 2013). "The Ewing's sarcoma cell lines A673, SK-ES-1, SK-N-MC and TC-71 also demonstrate hypoxic induction of HIF-1α and downstream genes." (PMID 20637078, 2010). "HIF-1α was predominantly localised in the nucleus of Ewing's tumour cells, whereas HIF-2α expression was mainly cytoplasmic." (PMID 20637078, 2010). "17/56 Ewing's tumours were HIF-1α-positive, 15 HIF-2α-positive and 10 positive for HIF-1α and HIF-2α." (PMID 20637078, 2010). "Co-localisation of HIF-1α and necrosis in Ewing's sarcoma suggests a role for hypoxia and/or hypoglycaemia in in vivo induction of HIF." (PMID 20637078, 2010). "As indicated by the elevated glucose uptake, increased lactate dehydrogenase activity and the stimulation of HIF-1α, only the Ewing sarcoma cells displayed aerobic glycolysis and, as in the previous report, melatonin reversed these changes and prevented the cytotoxicity of melatonin." (PMID 33466614, 2021). "PI3K/Akt/mTOR signaling was shown to regulate HIF-1α activation by hypoxia, as well as HIF1α-mediated resistance to hypoxia-induced apoptosis, in various human adult and pediatric cancers, including rhabdomyosarcoma and Ewing’s sarcomas, nasopharyngeal, colorectal, and glioma tumors." (PMID 34199959, 2021). "Melatonin inactivates HIF-1α in Ewing sarcoma cells, which could account for the decrease in aerobic glycolysis." (PMID 26252771, 2015). "In Ewing sarcoma, the tumor-associated chimeric gene EWS-FLI1 is known to induce the accumulation of hypoxia-induced transcription factor HIF-1α and cells have been recently shown to simultaneously activate mitochondrial respiration and high levels of glycolysis." (PMID 24391834, 2013). "Furthermore, it could be proposed that hypoxia may contribute to the aggressive metastatic behavior of Ewing sarcoma, as HIF-1α and EWS-FLI1 may function together in both synergistic and antagonistic cross-talk under hypoxia conditions." (PMID 26779435, 2015). "In our previous work we also identified HIF-1α as an important target modulating apoptosis resistance in pediatric tumors such as Rhabdomyosarcoma (RMS) and Ewing’s sarcoma (ES)." (PMID 23590596, 2013). "In Ewing’s sarcoma cells, EWS-FLI1 protein expression is upregulated by hypoxia in a HIF1α-dependent manner." (PMID 24216979, 2013). "HIF-1α and HIF-2α immunohistochemistry was performed on a Ewing's tumour tissue array." (PMID 20637078, 2010). "Of 56 Ewing's tumours assessed for expression of HIF; 30% expressed only HIF-1α, 27% only HIF-2α, 18% both HIF-1α and HIF-2α and 25% neither HIF isoform." (PMID 20637078, 2010).
Ewing sarcoma (continued). "Although there are a number of studies relating the activation of PI3K/AKT/mTOR pathway with the activation of HIF-1α, and melatonin regulates the PI3K/AKT/mTOR pathway in several models, our results show that these events are not connected in Ewing sarcoma cells." (PMID 26252771, 2015).